TOP3B (DNA topoisomerase III beta)
Description:
Releases the supercoiling and torsional tension of DNA introduced during the DNA replication and transcription by transiently cleaving and rejoining one strand of the DNA duplex. Introduces a single-strand break via transesterification at a target site in duplex DNA. The scissile phosphodiester is attacked by the catalytic tyrosine of the enzyme, resulting in the formation of a DNA-(5'-phosphotyrosyl)- enzyme intermediate and the expulsion of a 3'-OH DNA strand. The free DNA strand than undergoes passage around the unbroken strand thus removing DNA supercoils. Finally, in the religation step, the DNA 3'-OH attacks the covalent intermediate to expel the active-site tyrosine and restore the DNA phosphodiester backbone (By similarity). Possesses negatively supercoiled DNA relaxing activity.
Synonyms: TOP3B1
Tractability: PROTAC: ubiquitination databases record sites on it; its protein half-life has been measured.
Gene: Protein-coding gene on chromosome 22 (21,957,025 to 21,982,813, reverse strand). Ensembl gene ENSG00000100038.
Subcellular location (Human Protein Atlas): Nucleoplasm
Gene Ontology:
Molecular function: protein binding; RNA binding; RNA topoisomerase activity; DNA binding; DNA topoisomerase activity; DNA topoisomerase type I (single strand cut, ATP-independent) activity
Biological process: DNA topological change
Cellular component: DNA topoisomerase III-beta-TDRD3 complex; nucleus; condensed chromosome
Genetic constraint (gnomAD): Loss-of-function variants: 42 observed, 85.91 expected, observed/expected ratio (o/e) 0.49, 90% interval 0.38 to 0.63. The upper end of that interval is the gene's LOEUF score, 0.63, which puts it in group 2 of 6, group 1 being the genes least tolerant of losing a copy. Missense variants: 736 observed, 994.6 expected, observed/expected ratio (o/e) 0.74, 90% interval 0.7 to 0.79. Synonymous variants: 352 observed, 405.18 expected, observed/expected ratio (o/e) 0.87, 90% interval 0.8 to 0.95.
Homologues: Orthologues: chimpanzee TOP3B (99% identical), macaque TOP3B (99% identical), guinea pig TOP3B (97% identical), dog TOP3B (96% identical), mouse Top3b (96% identical), rabbit TOP3B (96% identical), rat Top3b (95% identical), pig TOP3B (94% identical), tropical clawed frog top3b (86% identical), zebrafish top3b (82% identical), Drosophila melanogaster Top3beta (58% identical), Caenorhabditis elegans Y48C3A.14 (54% identical). Paralogues in human: TOP3A (34% identical).
Diseases named in the same sentence as TOP3B in open-access papers:
TOP3B is named in the same sentence as 39 diseases in open-access papers, as found by Europe PMC text mining. Sharing a sentence is not in itself a finding about the gene and the disease. The quoted sentences say what the papers report.
schizophrenia (8 papers, 2015 to 2025). A major psychotic disorder characterized by abnormalities in the perception or expression of reality. "The P378Q (intellectual disability) and R472Q (schizophrenia) mutants produced similar levels of TOP3B•mRNA covalent intermediates, suggesting the overall TOP3B topoisomerase cycle was unaffected by either mutation." (PMID 41189056, 2025). "The loss and mutation of Topoisomerase 3β (TOP3B), the only known eukaryotic topoisomerase with the ability to catalyze RNA strand passage reactions, is linked to schizophrenia, autism, and intellectual disability." (PMID 41189056, 2025). "This dual activity is physiologically important as multiple neurological disorders, including schizophrenia, autism, and intellectual disability, are linked to TOP3B deletion and mutation." (PMID 41189056, 2025). "Three de novo TOP3B mutations have been identified in patients diagnosed with intellectual disability, schizophrenia, and autism spectrum disorder (P378Q, R472Q, and C666R, respectively)." (PMID 41189056, 2025). "mRNAs bound by TOP3B include those encoding proteins with neuronal functions related to schizophrenia and autism." (PMID 38534397, 2024). "The 247 kb microduplication at 22q11.22 in the patient CG0903 interrupted the TOP3B, whose mutations were associated with several neurodevelopmental disorders including schizophrenia, autism, and epilepsy." (PMID 34659328, 2021). "The case for TOP3B playing a role in neurogenesis is strong with studies in fly and mice showing neural defects as a result of TOP3B disruption and human TOP3B disrupted patients are predisposed to autism and schizophrenia." (PMID 31795919, 2019). "This is in contrast with other studies that have linked the TOP3B gene to autism and schizophrenia and juvenile myoclonic epilepsy." (PMID 31795919, 2019). "A study of an isolated northern Finnish family found that the TOP3B gene was associated with schizophrenia and cognitive impairment." (PMID 31795919, 2019). "Two studies have shown that single nucleotide and copy number variants of TOP3B are enriched in individuals with schizophrenia and ASD." (PMID 26201030, 2015). "Recently, deletions of TOP3B were shown to be associated with both schizophrenia and intellectual disability." (PMID 26201030, 2015). "TOP3B is enriched at multiple mRNAs with neural functions related to autism and schizophrenia." (PMID 31795919, 2019). "At the molecular levels, we find that Top3b deficiency causes a statistically significant increase in the neutrophil-to-lymphocyte ratio (NLR), a marker of systemic inflammation and of diseases including infectious and autoimmune disorders, schizophrenia and cancer." (PMID 40568167, 2025).
autism (6 papers, 2017 to 2025). Persistent deficits in social interaction and communication and interaction as well as a markedly restricted repertoire of activity and interest as well as repetitive patterns of behavior. "Our data show that the autism-linked C666R mutation results in accumulation of unresolved TOP3B•mRNA covalent intermediates." (PMID 41189056, 2025). "GABAergic signaling plays an indispensable role in neural development by regulating adult neurogenesis, and its disruption has been linked to autism and schizophrenia, diseases associated with Top3b mutations." (PMID 36909584, 2023). "Duplication of GABA receptor genes and deletion of TOP3B (DNA Topoisomerase III Beta is a protein-coding gene), a topoisomerase involved in the relaxation of supercoiled DNA, contribute to autism susceptibility." (PMID 34209997, 2021). "However, a significant increase in TOP3B•mRNA covalent intermediates were detected with the autism-linked C666R mutant, partially phenocopying the “self-trapping” R338W mutant." (PMID 41189056, 2025). "One of the siblings with the TOP3B duplication had a history of an autism diagnosis but did not currently present with significant autism symptoms." (PMID 29090080, 2017). "The only individual in our analyses with autism in the BD/CD group carried a duplication of LCR-B to D. She had one sibling with the same LCR-B to D duplication and two siblings with a duplication of TOP3B (in a small region between LCR-E and F)." (PMID 29090080, 2017).
Cognitive impairment (5 papers, 2022 to 2025). Abnormal cognition is characterized by deficits in thinking, reasoning, or remembering. "Many of the cellular and behavioral phenotypes connected to cognitive impairment and psychiatric disorders are also observed in multiple animal models harboring TOP3B deletion or mutations." (PMID 41189056, 2025). "None of them showed the VCFS/DGS episignature, including two cases (GM151544 and GM191550) with distal low-copy-number repeat sequence (LCR)-DE deletions that included TOP3B (OMIM∗ 603582), which is associated with cognitive impairment and facial dysmorphisms." (PMID 38751117, 2024). "Characterization of TOP3B or TDRD3 knockout mice suggested defective neuronal activity-dependent transcription as well as defective post-transcriptional regulation as mechanisms behind the cognitive impairment." (PMID 38534397, 2024). "The findings that two major interacting partners of TDRD3, TOP3B and FMRP, are linked to psychiatric and cognitive disorders imply that TDRD3 itself could be associated with the same disorders." (PMID 36909584, 2023). "We infer that the entire Top3b-Tdrd3 complex is essential for normal brain function, and that defective post-transcriptional regulation could contribute to cognitive impairment and psychiatric disorders." (PMID 36909584, 2023). "TOP3B null mice (which mimics the most common deletion observed in the human population) display reduced fertility and life span, autoimmunity, impaired synapse formation, abnormal adult hippocampal neurogenesis, and behavioral abnormalities tied to cognitive impairment and psychiatric disorders." (PMID 41189056, 2025). "A major objective of this study is to establish a mouse model to examine a hypothesis that Tdrd3 may resemble its two partners (Top3b and FMRP) in playing important roles in psychiatric and cognitive disorders." (PMID 36909584, 2023).
epilepsy (3 papers, 2020 to 2023). A brain disorder characterized by episodes of abnormally increased neuronal discharge resulting in transient episodes of sensory or motor neurological dysfunction, or psychic dysfunction. "Thrombospondin-1 (THBS1) and DNA topoisomerase 3-beta-1 (TOP3B), proteins reported to be associated with various forms of epilepsy, were also over-represented in SCG patients compared with IE." (PMID 32823271, 2020).
Intellectual disability (3 papers, 2015 to 2025). "For example, TOP3B null Drosophila demonstrate neuromuscular junction abnormalities, which is a known phenotype in FmrI null flies and in patients with Fragile X syndrome, a genetic disorder that also causes intellectual disability." (PMID 41189056, 2025). "Moderate and severe intellectual disability was observed in cases with distal deletions, highlighting the involvement of the TOP3B gene." (PMID 36360320, 2022).
renal carcinoma (3 papers, 2019 to 2025). A carcinoma arising from the epithelium of the renal parenchyma or the renal pelvis. "Top3b loss-associated accumulation of R-loops and subsequent DNA damage were reported in human renal cancer." (PMID 40568167, 2025). "Impaired Top3b activity has also been related to mammary gland cancer, bilateral renal cancer, lymphoma and melanoma." (PMID 40568167, 2025). "A novel homozygous deletion was found that included TOP3B was found on an Infinium Omni2.5 (Illumina) microarray in an individual with bilateral renal cancer." (PMID 39095811, 2024). "Our new data, using lymphoblasts from a bilateral renal cancer patient deleted for TOP3B, show multiple hallmarks of genome instability that were pheno-copied in modelled TOP3B null cells of a different lineage." (PMID 31795919, 2019). "A homozygous deletion for the TOP3B gene was identified in a patient with bilateral renal cancer." (PMID 31795919, 2019).
breast carcinoma (2 papers, 2020 to 2023). "Because TOP3B has been reported to be ubiquitylated and targeted for proteasomal degradation in MCF7 breast cancer cells in the absence of TDRD310, we measured the ubiquitylation of TOP3B in TDRD3-depleted cells (i.e., in siTDRD3-transfected HEK293 cells and in TDRD3KO HCT116 cells)." (PMID 37980342, 2023).
colon cancer (2 papers, 2023 to 2024). "A study of TOP3B or TDRD3 knockout in human HCT116 colon cancer cells indicated that TOP3B–TDRD3 can regulate mRNA translation and turnover with mechanisms that may not always depend on the TOP3B topoisomerase activity." (PMID 38534397, 2024).
invasive breast carcinoma (2 papers, 2016 to 2017). A carcinoma that infiltrates the breast parenchyma. "High expression of TOP3B was reported to be correlated to worse disease-specific survival and metastasis-free survival in patients with invasive breast cancers." (PMID 28355294, 2017).
Anxiety (1 paper, 2023). Intense feelings of nervousness, tension, or panic often arise in response to interpersonal stresses. "For example, Tdrd3-null mice exhibit reduced anxiety in several behavior assays, which is opposite to Top3b-null mice, which show increased anxiety." (PMID 36909584, 2023). "Collectively, these results indicate reduced anxiety in Tdrd3-null mice, a phenotype that is directly opposite to Top3b-null mice, which show increased anxiety in a nearly identical battery of tests." (PMID 36909584, 2023). "The defects found only in Tdrd3-null mice include reduced anxiety and myelination as well as elevated neuron complexity, suggesting that Tdrd3 may also have function(s) independently of Top3b." (PMID 36909584, 2023). "We gave Tdrd3-null mice a panel of behavior tests to examine whether they exhibit cognitive and anxiety abnormalities comparable to Top3b-null and other mouse models of psychiatric disorders." (PMID 36909584, 2023).
autoimmune disorders (1 paper, 2025). "Top3b-KO mice also have a shorter life-span, infertility after successive generation of homozygous pairs breeding, transcriptional and behavioral impairment, accumulation of chromosomal aberrations, and are prone to autoimmune disease." (PMID 40568167, 2025).
clear cell renal carcinoma (1 paper, 2019). A malignant epithelial neoplasm of the kidney characterized by the presence of lipid-containing clear cells within a vascular network. "The TOP3B null patient showed no mental illness, but instead presented with bilateral clear cell renal cancer and multifocal and nodular lesions." (PMID 31795919, 2019).
dermatitis (1 paper, 2025). An inflammatory process affecting the skin. "Consistent with previous report, our Top3b-KO mice showed reduced lifespan and increased incidence of dermatitis." (PMID 40568167, 2025).
lymphoid tumors (1 paper, 2025). "By studying Top3b knockout mice (Top3b-KO), we find that the loss of Top3b accelerates the development of spontaneous lymphoid tumors arising in spleens and lymph nodes, the organs with prominent Top3b expression." (PMID 40568167, 2025).
lymphoma (1 paper, 2025). A malignant (clonal) proliferation of B- lymphocytes or T- lymphocytes which involves the lymph nodes, bone marrow and/or extranodal sites. "Since EL4 cells were derived from a malignant T-cell lymphoma induced in a C57BL/6 inbred mouse strain, this model allowed us to compare the impact of a functional (WT) and Top3b-deficient microenvironment on lymphoma growth." (PMID 40568167, 2025). "Together, these data show that loss of Top3b is associated with enhanced lymphoma development suggesting a tumor suppressor role for Top3b." (PMID 40568167, 2025). "In summary, our findings demonstrate that Top3b-KO mice develop a complex phenotype linking Top3b deficiency with R-loop mediated genomic instability that triggers immune dysregulation and lymphoma-prone phenotype of Top3b-KO mice." (PMID 40568167, 2025). "Collectively, these data demonstrate that loss of Top3b promotes lymphoma growth." (PMID 40568167, 2025). "Of 35 Top3b-KO female mice necropsied at 18–24 months of age, lymphomas were observed in 15 animals versus 3/21 in WT mice (43 % vs. 14.3%, respectively, p < 0.05)." (PMID 40568167, 2025). "In agreement with published studies, we find that Top3b-KO mice display a shorterned life span, which we attribute, at least in part to increased lymphoma burden, especially in females mice." (PMID 40568167, 2025). "As a result, syngeneic EL4 lymphomas in Top3b-KO recipients reached an experimental tumor size limit of ≤ 20 mm at 21 days after transplantation, significantly earlier than in the WT control mice." (PMID 40568167, 2025). "Herein, we report that genetic inactivation of Top3b promotes syngeneic lymphoma growth in young adult mice and accelerates spontaneous lymphomagenesis in aging mice." (PMID 40568167, 2025). "Because elevated activation of the cGAS-STING pathway has been associated with peripheral T-cell lymphomas and we found the Top3b-KO mice to be immune-compromized, we used a lymphoma syngeneic model and compared tumor development in Top3b-KO and WT mice." (PMID 40568167, 2025). "EL4 lymphoma cells were readily engrafted both in WT and Top3b-KO recipients." (PMID 40568167, 2025). "At 11–15 months of age, histological analysis of spleens detected early lymphomas in 3 out of 13 Top3b-KO mice in comparison with none in the age-matched WT littermates." (PMID 40568167, 2025).
lymphopenia (1 paper, 2025). Reduction in the number of lymphocytes. "Aging Top3b-KO mice also display splenomegaly and systemic immune alterations including neutrophilia and lymphopenia suggestive of chronic inflammation." (PMID 40568167, 2025).
Splenomegaly (1 paper, 2025). Abnormal increased size of the spleen. "Collectively, these results demonstrate that Top3b loss drives splenomegaly and an inflammatory phenotype." (PMID 40568167, 2025). "In the Top3b-KO mice progressing towards splenomegaly, the total number of splenocytes was increased, reaching more than a 2-fold difference by 11–15 months of age as compared to WT controls." (PMID 40568167, 2025). "Upon aging, we find that Top3b mice exhibit features of immune system dysfunctions including splenomegaly, inflammatory cell infiltration in different organs, and a higher frequency of ulcerative dermatitis, which is consistent with the prior report from Shaw and Wang." (PMID 40568167, 2025).
T-cell lymphomas (1 paper, 2025). "Moreover, knocking-out Top3b promotes the rapid development of syngeneic EL4 T-cell lymphomas." (PMID 40568167, 2025).
viral infection (1 paper, 2025). "It is unclear if TOP3B itself is packaged into viral particles, however if this is the case it may be used to unwrap the UUKV RNA from the viral nucleocapsid to promote initial viral infection." (PMID 40758761, 2025).